GDPD4 (glycerophosphodiester phosphodiesterase domain containing 4)
Description:
Ecto-phospholipase that cleaves the phosphodiester bond in the glycosylphosphatidylinositol (GPI) anchor of TRABD2A and TRABD2B, releasing them from the plasma membrane. The release in the extracellular space inactivates these metalloproteases involved in the negative regulation of Wnt signaling.
Synonyms: GDE6; UGPQ
Tractability: Antibody: UniProt predicts a signal peptide or a membrane-spanning region.
Gene: Protein-coding gene on chromosome 11 (77,216,558 to 77,301,687, reverse strand). Ensembl gene ENSG00000178795.
Subcellular location: Cell membrane
Gene Ontology:
Molecular function: glycerophosphodiester phosphodiesterase activity; phosphoric diester hydrolase activity
Biological process: lipid metabolic process
Cellular component: plasma membrane; membrane
Genetic constraint (gnomAD): Loss-of-function variants: 25 observed, 33.28 expected, observed/expected ratio (o/e) 0.75, 90% interval 0.55 to 1.05. The upper end of that interval is the gene's LOEUF score, 1.05, which puts it in group 4 of 6, group 1 being the genes least tolerant of losing a copy. Missense variants: 394 observed, 426.43 expected, observed/expected ratio (o/e) 0.92, 90% interval 0.85 to 1. Synonymous variants: 143 observed, 147.71 expected, observed/expected ratio (o/e) 0.97, 90% interval 0.84 to 1.11.
Homologues: Orthologues: chimpanzee GDPD4 (95% identical), macaque GDPD4 (91% identical), dog GDPD4 (68% identical), mouse Gdpd4 (65% identical), rat Gdpd4 (64% identical), guinea pig GDPD4 (62% identical), tropical clawed frog gdpd4 (43% identical), zebrafish gdpd4b (39% identical), zebrafish gdpd4a (32% identical). Paralogues in human: GDPD5 (37% identical), GDPD2 (34% identical), GDPD1 (12% identical), GDE1 (12% identical), GDPD3 (11% identical).
Diseases named in the same sentence as GDPD4 in open-access papers:
GDPD4 is named in the same sentence as 5 diseases in open-access papers, as found by Europe PMC text mining. Sharing a sentence is not in itself a finding about the gene and the disease. The quoted sentences say what the papers report.
autism (1 paper, 2012). Persistent deficits in social interaction and communication and interaction as well as a markedly restricted repertoire of activity and interest as well as repetitive patterns of behavior. "In a previous report, loss of GDPD4 was found as a low frequency de novo CNV in autism patients (3 autism from 1683 analyzed) but not in normal controls." (PMID 22909152, 2012).
gastric cancer (1 paper, 2023). A primary or metastatic malignant neoplasm involving the stomach. "The mRNA levels of RAI14, GUCY1A2, CNGB3, FJX1, FZD2, ELOVL2, and GDPD4 were all expressed upregulated in gastric cancer tissues, except for CXCL13, whose expression level was not significantly different between gastric cancer tissues and normal cell lines." (PMID 36823639, 2023).
GDPD4 also shares sentences with these, for which no sentence is quoted: embryonal tumors (1 paper); infection (1); prostate carcinoma (1).